TARS1 (threonyl-tRNA synthetase 1)
Description:
Catalyzes the attachment of threonine to tRNA(Thr) in a two-step reaction: threonine is first activated by ATP to form Thr-AMP and then transferred to the acceptor end of tRNA(Thr). Also edits incorrectly charged tRNA(Thr) via its editing domain, at the post-transfer stage (By similarity).
Synonyms: ThrRS; TARS; TTD7
Tractability: Small molecule: a structure with a bound ligand is known; a high-quality ligand is known; it belongs to a druggable protein family. PROTAC: UniProt records ubiquitination sites on it; ubiquitination databases record sites on it; a small molecule that binds it is known.
Target class: Enzyme; Ligase
Gene: Protein-coding gene on chromosome 5 (33,440,696 to 33,469,531, forward strand). Ensembl gene ENSG00000113407.
Subcellular location: Cytoplasm
Subcellular location (Human Protein Atlas): Cytosol; Actin filaments
Pathways (Reactome):
Metabolism of proteins: Cytosolic tRNA aminoacylation
Gene Ontology:
Molecular function: ATP binding; identical protein binding; protein binding; threonine-tRNA ligase activity; zinc ion binding; aminoacyl-tRNA ligase activity; nucleotide binding
Biological process: threonyl-tRNA aminoacylation; tRNA aminoacylation; tRNA aminoacylation for protein translation
Cellular component: extracellular exosome; cytoplasm; cytosol
Genetic constraint (gnomAD): Loss-of-function variants: 51 observed, 91.11 expected, observed/expected ratio (o/e) 0.56, 90% interval 0.45 to 0.71. The upper end of that interval is the gene's LOEUF score, 0.71, which puts it in group 2 of 6, group 1 being the genes least tolerant of losing a copy. Missense variants: 769 observed, 878.52 expected, observed/expected ratio (o/e) 0.88, 90% interval 0.82 to 0.93. Synonymous variants: 300 observed, 292.99 expected, observed/expected ratio (o/e) 1.02, 90% interval 0.93 to 1.13.
Homologues: Orthologues: chimpanzee TARS1 (99% identical), macaque TARS1 (99% identical), rabbit TARS1 (96% identical), dog TARS1 (95% identical), mouse Tars1 (95% identical), rat Tars1 (94% identical), guinea pig TARS1 (93% identical), pig TARS1 (92% identical), tropical clawed frog tars1 (88% identical), zebrafish tars1 (84% identical). Paralogues in human: TARS3 (72% identical), TARS2 (52% identical), PARS2 (12% identical), MRPL39 (11% identical).
Diseases named in the same sentence as TARS1 in open-access papers:
TARS1 is named in the same sentence as 25 diseases in open-access papers, as found by Europe PMC text mining. Sharing a sentence is not in itself a finding about the gene and the disease. The quoted sentences say what the papers report.
ovarian carcinoma (4 papers, 2014 to 2024). A malignant neoplasm originating from the surface ovarian epithelium. "Indeed, they have found that ovarian cancer cells secrete TARS1, and patient serum TARS1 levels correlate with TARS1 expression in tumor samples." (PMID 38477373, 2024). "Indeed, overexpression of TARS1 correlates with angiogenic markers and progression of ovarian cancer." (PMID 33266490, 2020).
pancreatic cancer (3 papers, 2022 to 2024). "A canonical function of TARS1 has been suggested in pancreatic cancer, where the overexpression of Mucin1 (MUC1) and cell migration are dependent on high levels of TARS1 due to an unusually high number of threonine residues in the amino acid sequence of MUC1." (PMID 38477373, 2024). "Previous work in pancreatic cancer cells demonstrated that threonine starvation or knockdown of TARS1 decreases mucin 1 (MUC1) protein levels." (PMID 38956874, 2024).
breast carcinoma (2 papers, 2021 to 2023). "The overexpression of TARS1 has been found in several malignant tumors, including breast cancer, and has been linked to poor prognoses." (PMID 37637061, 2023). "Breast cancer patient clinicopathological characteristics were quantified using immunohistochemistry, and it was discovered that overexpression of TARS1 was linked to higher initial tumor sizes and hormone receptor negativity." (PMID 37637061, 2023). "In conclusion, the association of TARS1 overexpression and clinicopathological features of breast cancer targets a possible beneficiary population for its clinical translation." (PMID 37637061, 2023). "First, we used bioinformatics methods to analyze TARS1(encoding cytoplasmicthreonyl-tRNA synthetase) expression, prognosis, and clinicopathological characteristics in TCGA database breast cancers, and then we collected breast cancer specimens from our center for validation." (PMID 37637061, 2023). "Overall, our study found that TARS1 may be a causative gene in breast cancer and is more significantly overexpressed in breast cancers with specific clinicopathological features." (PMID 37637061, 2023). "Then, using GSEA analysis, GO/KEGG pathway enrichment analysis, and breast cancer immune infiltration analysis, the potential benefit of TARS1 for breast cancer treatment was investigated." (PMID 37637061, 2023). "TARS1 overexpression in breast cancer was demonstrated at the mRNA and protein levels in fresh frozen tissue and paraffin-embedded tissue, respectively." (PMID 37637061, 2023). "Based on the median expression of TARS1, breast cancers from TCGA-BRCA Database (removed duplicate samples and those lacking clinical information) were divided into low and high expression groups and immune cell infiltration was separately analyzed." (PMID 37637061, 2023). "By knocking down TARS1, breast cancer cells were prevented from proliferating and invading, as well as exhibiting other malignant biological properties." (PMID 37637061, 2023). "TARS1 is overexpressed in breast cancer at both the transcriptional and translational levels, according to quantitative analysis of breast cancer specimens obtained at our center." (PMID 37637061, 2023). "Contrarily, TARS1 was significantly overexpressed in breast cancer samples from both paired and unpaired individuals." (PMID 37637061, 2023). "KM plotter data showed that breast cancer groups with high TARS1 had significantly lower overall survival rates (HR=1.71, P=0.001), progress-free interval (HR=1.82, P=0.001), and disease-specific survival (HR=1.86, P=0.006)." (PMID 37637061, 2023). "TARS1 was also found to be co-expressed with the majority of immune checkpoint-related genes, and breast cancer with TARS1 overexpression responded better to immunotherapy." (PMID 37637061, 2023). "As a last step, we examined TARS1’s effects on breast cancer cell behavior with cellular assays." (PMID 37637061, 2023). "TARS1 overexpression leads to a suppressed state of immune infiltration within breast cancer and may be a predictive biomarker for the efficacy of immunotherapy in breast cancer." (PMID 37637061, 2023). "According to our study, TARS1 may be an oncogene in breast cancer and may be a biomarker of efficacy or a target of immunotherapy in breast cancer." (PMID 37637061, 2023). "This could be one of the reasons why TARS1 overexpression enhances breast cancer cell proliferation and migration, ultimately leading to a poor prognosis for patients with breast cancer." (PMID 37637061, 2023). "Consequently, TARS1 overexpression aligns with the heightened metabolic state of cancer cells, potentially contributing to the promotion of breast cancer proliferation and migration." (PMID 37637061, 2023). "TARS1 was then subjected to GSEA (Gene Set Enrichment Analysis) enrichment analysis, GO/KEGG pathway enrichment analysis, and breast cancer immune infiltration characterization." (PMID 37637061, 2023).
breast carcinoma (continued). "In our study, we discovered that TARS1 overexpression inhibited the infiltration of anti-cancer immune cells like CD8+ T cells and NK cells while promoting the infiltration of oncogenic immune cells like Treg and Th2 in breast cancer." (PMID 37637061, 2023). "TARS1 was successfully knocked down in MDA-MB-231, SKBR3 and MCF-7 cells using siRNA, and CCK8 and clone formation assays revealed that breast cancer cell proliferation was significantly reduced." (PMID 37637061, 2023). "Breast cancers with large primary tumors and negative hormone receptors are more likely to overexpress TARS1." (PMID 37637061, 2023). "Overexpression of TARS1 promotes the infiltration of T cells, such as Tregs and Th2s, while inhibiting the infiltration of NK cells and CD8+ T cells, which are anticancer cells in breast cancer." (PMID 37637061, 2023). "As of yet, no clear understanding of TARS1’s role in breast cancer has been established." (PMID 37637061, 2023).
lung carcinoma (1 paper, 2025). "TARS1 knockdown in H1703 cells drastically reduces tumor formation and growth in a xenograft mouse model, consistent with poor patient survival in lung cancer with high TARS1 expression." (PMID 41380973, 2025). "Elevated TARS1 expression in lung cancer correlates with poor patient survival." (PMID 41380973, 2025).
lung disease (1 paper, 2024). "Overall, our data indicate that phenotypic heterogeneity will ultimately be observed in human TARS1-related recessive disease, and that individuals with bi-allelic TARS1 variants should be carefully evaluated for lung disease." (PMID 38956874, 2024).
lymph node metastases (1 paper, 2023). "However, our results suggest that TARS1 overexpression is more pronounced in patients with lymph node metastases, independent of HER-2 expression, which is different from the bioinformatic results and requires further validation with larger volume samples." (PMID 37637061, 2023).
small cell lung carcinoma (1 paper, 2025). Small cell lung cancer (SCLC) is a highly aggressive malignant neoplasm, accounting for 10-15% of lung cancer cases, characterized byrapid growth, and early metastasis. "We find that overexpression of TARS1 supports non–small cell lung cancer cell proliferation in vitro, tumor formation of xenografts in mice, and hyperactivity of STAT3." (PMID 41380973, 2025).
cancer (9 papers, 2014 to 2025). A tumor composed of atypical neoplastic, often pleomorphic cells that invade other tissues. "Future investigation taking advantage of resources such as the Cancer Dependency Map and a recently developed deep learning model can lead to a broader understanding of TARS1’s role in cancer." (PMID 41380973, 2025). "To probe the role of TARS1 in promoting cancer cell growth in vivo, we performed mouse xenograft experiments by grafting nude mice with H1703 cells treated with shTARS1 or shScramble lentivirus." (PMID 41380973, 2025). "Specific aaRSs that are differentially upregulated across many cancer types include TARS1 (n = 23), DARS2 (n = 22), GARS1 (n = 21), YARS2 (n = 21), EPRS1 (n = 20), AIMP2 (n = 19), and FARSA (n = 18)." (PMID 33266490, 2020). "A potential link of TARS1 to cancer was speculated based on the epidemiological connection between myositis and cancer." (PMID 38477373, 2024). "Since mucin is believed to be crucial for cancer cell migration, TARS1 catalytic inhibitors could be applied to control cancer metastasis." (PMID 37212275, 2023). "TARS1 was overexpressed in 15 cancers according to a pan-cancer study." (PMID 37637061, 2023). "It is tempting to speculate that these identified and unidentified cancer-promoting activities of TARS1/2 may share regulation related to their cognate amino acid threonine." (PMID 33266490, 2020). "The TARS1 protein has an extracellular pro-angiogenic activity, which could explain its strong gene amplification in cancers." (PMID 33266490, 2020). "TARS1, VARS1, CARS2, DARS2, and YARS2 are associated with unfavorable outcomes in two cancer types." (PMID 33266490, 2020). "TARS1/2 are frequently altered in cancer patients, predominantly through gene amplifications, which may reflect a shared functional dysregulation of TARS1/2 in cancer." (PMID 33266490, 2020). "At least, the result of R441A suggests that TARS1 has a role in promoting cancer cell proliferation through a nontranslational mechanism." (PMID 41380973, 2025). "Our current study uncovers a novel mechanism of STAT3 activation by TARS1, which may operate in cancer as well as noncancer cells." (PMID 41380973, 2025). "Data from our reconstitution experiments expressing recombinant TARS1, STAT3, and JAK in HEK293 cells also suggest that the scaffolding mechanism does not require a cancer-specific cellular context." (PMID 41380973, 2025). "In contrast to the pro-angiogenic activity of TARS1, SARS1 possesses anti-angiogenic activity through its nuclear presence, which may explain its lack of amplification in cancer tissues." (PMID 33266490, 2020).
tumor (8 papers, 2020 to 2025). "As a final step, we assessed TARS1’s potential to predict immunotherapy effectiveness using TIDE (Tumor Immune Dysfunction and Exclusion), by analyzing its co-expression with immune checkpoint-related genes." (PMID 37637061, 2023). "Specifically looking at the cytoplasmic aaRS members, the genes that are preferentially amplified across most tumor types are TARS1, GARS1, MARS1, AIMP2, and AIMP3/EEF1E1." (PMID 33266490, 2020). "Furthermore, while all the mice injected with control H1703 cells developed tumors, 23% of the mice injected with TARS1 knockdown cells did not form any tumor within 100 days of grafting." (PMID 41380973, 2025).
infection (7 papers, 2015 to 2025). The state of being infected such as from the introduction of a foreign agent such as serum, vaccine, antigenic substance or organism. "Quite the contrary, many clones targeting genes required for translation, including those encoding aminoacyl-tRNA synthetases (hars-1, lars-1, rars-1, tars-1, wars-1) and eIF subunits, were required for expression of nlp-29 after infection." (PMID 27129311, 2016). "On the contrary, MOPV infection led to the late (48 h) release of PSMD2, RPS11, HNRNPA3, ATP1A1, TARS1, and PRKAR1A, whereas significantly elevated levels of IGFBP3 were found at both timepoints." (PMID 35337059, 2022).
TARS1 also shares sentences with these, for which no sentence is quoted: dermatomyositis (2 papers); endometrial cancer (2); polymyositis (2); adenocarcinoma (1); autoimmune disease (1); diabetes (1); endocarditis (1); gastric cancer (1); genetic disorders (1); glaucoma (1); Hypertension (1); infiltrating ductal carcinoma (1); melanoma (1); osteosarcoma (1); peritonitis (1).